PWWP2A (PWWP domain containing 2A)
Description:
Chromatin-binding protein that acts as an adapter between distinct nucleosome components (H3K36me3 or H2A.Z) and chromatin-modifying complexes, contributing to the regulation of the levels of histone acetylation at actively transcribed genes. Competes with CHD4 and MBD3 for interaction with MTA1 to form a NuRD subcomplex, preventing the formation of full NuRD complex (containing CHD4 and MBD3), leading to recruitment of HDACs to gene promoters resulting in turn in the deacetylation of nearby H3K27 and H2A.Z. Plays a role in facilitating transcriptional elongation and repression of spurious transcription initiation through regulation of histone acetylation (By similarity). Essential for proper mitosis progression.
Synonyms: KIAA1935; MST101
Tractability: PROTAC: UniProt records ubiquitination sites on it.
Gene: Protein-coding gene on chromosome 5 (160,061,801 to 160,119,478, reverse strand). Ensembl gene ENSG00000170234.
Subcellular location: Nucleus
Subcellular location (Human Protein Atlas): Nucleoplasm; Focal adhesion sites
Pathways (Reactome):
Chromatin organization: NuRD complex assembly
Gene Ontology:
Molecular function: chromatin binding; histone binding; histone H3K36me3 reader activity; NuRD complex binding; protein binding
Biological process: chromatin remodeling; positive regulation of transcription elongation by RNA polymerase II; regulation of transcriptional start site selection at RNA polymerase II promoter
Cellular component: nucleoplasm; nucleus
Genetic constraint (gnomAD): Loss-of-function variants: 18 observed, 44.55 expected, observed/expected ratio (o/e) 0.4, 90% interval 0.28 to 0.6. The upper end of that interval is the gene's LOEUF score, 0.6, which puts it in group 2 of 6, group 1 being the genes least tolerant of losing a copy. Missense variants: 867 observed, 932.84 expected, observed/expected ratio (o/e) 0.93, 90% interval 0.88 to 0.98. Synonymous variants: 396 observed, 358.68 expected, observed/expected ratio (o/e) 1.1, 90% interval 1.02 to 1.2.
Homologues: Orthologues: chimpanzee PWWP2A (99% identical), macaque PWWP2A (99% identical), rabbit PWWP2A (95% identical), dog PWWP2A (92% identical), rat Pwwp2a (85% identical), mouse Pwwp2a (84% identical), guinea pig PWWP2A (78% identical), tropical clawed frog pwwp2a (65% identical), zebrafish pwwp2a (30% identical). Paralogues in human: PWWP2B (26% identical), DNMT3A (16% identical), DNMT3B (13% identical), DNMT3L (5% identical).
Diseases named in the same sentence as PWWP2A in open-access papers:
PWWP2A is named in the same sentence as 4 diseases in open-access papers, as found by Europe PMC text mining. Sharing a sentence is not in itself a finding about the gene and the disease. The quoted sentences say what the papers report.
Hepatic fibrosis (2 papers, 2019 to 2024). The presence of excessive fibrous connective tissue in the liver. "Inhibiting circ-PWWP2A alleviated hepatic fibrosis in vivo, suggesting that circ-PWWP2A serves as a common downstream mediator of TGF-β and LPS in HSC activation and fibrogenesis." (PMID 38977131, 2024). "Taken together, these data suggested that downregulating circ-PWWP2A alleviated hepatic fibrosis in vivo." (PMID 31719209, 2019). "Furthermore, downregulating circ-PWWP2A was indicated to alleviate hepatic fibrosis in vivo." (PMID 31719209, 2019).
fibrosis (1 paper, 2019). the formation of excess fibrous connective tissue in an organ or tissue in a reparative or reactive process. "The downregulation of circ-PWWP2A in fibrosis mouse model attenuates hepatic fibrogenesis, which applied the basis for developing therapeutic strategy in the future." (PMID 31719209, 2019). "Then, its expression in CCl4-induced fibrosis mouse model was further detected, and the expression of mmu_circ_0000254 (the circ-PWWP2A in mouse genome) was markedly higher in fibrotic liver tissues than that in normal liver tissues." (PMID 31719209, 2019).
PWWP2A also shares sentences with these, for which no sentence is quoted: Azoospermia (1 paper); tumor (1).